ITPRIPL2 (ITPRIP like 2)
Synonyms: FLJ22994; MGC126798; MGC126800; LOC162073; D1C
Tractability: Antibody: UniProt predicts a signal peptide or a membrane-spanning region.
Gene: Protein-coding gene on chromosome 16 (19,113,932 to 19,121,629, forward strand). Ensembl gene ENSG00000205730.
Subcellular location: Membrane
Subcellular location (Human Protein Atlas): Centrosome
Gene Ontology:
Cellular component: membrane
Genetic constraint (gnomAD): Loss-of-function variants: 29 observed, 29.45 expected, observed/expected ratio (o/e) 0.98, 90% interval 0.73 to 1.34. The upper end of that interval is the gene's LOEUF score, 1.34, which puts it in group 5 of 6, group 1 being the genes least tolerant of losing a copy. Missense variants: 696 observed, 699.5 expected, observed/expected ratio (o/e) 0.99, 90% interval 0.93 to 1.06. Synonymous variants: 344 observed, 320.38 expected, observed/expected ratio (o/e) 1.07, 90% interval 0.98 to 1.17.
Homologues: Orthologues: chimpanzee ITPRIPL2 (100% identical), pig ITPRIPL2 (90% identical), macaque ITPRIPL2 (90% identical), mouse Itpripl2 (85% identical), rat Itpripl2 (85% identical), guinea pig ITPRIPL2 (83% identical), rabbit ITPRIPL2 (83% identical). Paralogues in human: ITPRIP (19% identical), ITPRIPL1 (18% identical), CGAS (16% identical), MB21D2 (15% identical), TMEM102 (14% identical), MAB21L4 (12% identical), MAB21L2 (11% identical), MAB21L3 (11% identical), MAB21L1 (10% identical).
Diseases named in the same sentence as ITPRIPL2 in open-access papers:
ITPRIPL2 is named in the same sentence as 1 disease in open-access papers, as found by Europe PMC text mining. Sharing a sentence is not in itself a finding about the gene and the disease. The quoted sentences say what the papers report.
gastric cancer (1 paper, 2022). A primary or metastatic malignant neoplasm involving the stomach. "The MYOF, CLIP1, AHNAK, ANXA2, ITPRIPL2 and LEPROT genes in tissues of patients with gastric cancer were found to be altered by amplification, extensive deletion, truncating mutations, splice mutations, missense mutations, and high/low mRNA expression." (PMID 36147922, 2022).